NEDD9 (neural precursor cell expressed, developmentally down-regulated 9)
Diseases named in the same sentence as NEDD9 in open-access papers (continued):
Sharing a sentence is not in itself a finding about the gene and the disease.
cancer (continued). "In fact, it has been shown that Twist1 induces the motile stem-like cancer cell phenotype via the activation of the Twist1-let-7i-NEDD9 axis leading to RAC1 activation." (PMID 27074574, 2016). "Nedd9 is a scaffold protein localized in focal adhesion that is involved in the development and progression of cancer cells." (PMID 27336669, 2016). "NEDD9 is an adhesion docking molecule and high levels of NEDD9 has been observed in many cancer types including PA." (PMID 25536063, 2014). "Analysis of phosphopeptide data at PhosphositePlus also confirmed frequent detection of phosphorylated human p130Cas Y249 (detected in >600 records) and NEDD9 Y214 in a variety of cancer cell lines." (PMID 23874939, 2013). "The Cas family protein NEDD9/HEF1/Cas-L has emerged as a critical regulator of cancer invasion and metastasis in a variety of different cancers." (PMID 23874939, 2013). "Given the important role of this protein in promoting cancer invasion, greater understanding of the function of the individual tyrosine residues is important for the future design of approaches to target NEDD9 to arrest cancer cell invasion." (PMID 23874939, 2013). "We are currently identifying key domains of NEDD9 that binds to CSPG4 to further understand the mechanisms of cancer progression and metastasis." (PMID 22984505, 2012). "The multi-functional adaptor protein NEDD9/HEF1/Cas-L regulates cell motility, invasion and cell cycle progression, and plays key roles in cancer progression and metastasis." (PMID 20825672, 2010). "The cancer-promoting proteins Aurora A and HEF1/NEDD9/CAS-L have a role in primary cilium stabilization." (PMID 19439065, 2009). "LPXN [GenBank:NM_004811] and NEDD9 [GenBank:NM_006403] have been reported as being involved in cancer progression." (PMID 18928525, 2008). "The importance of balancing opposing activities in cancer is illustrated by genes such as HEF1 (NEDD9), a metastasis-related gene and HMMR, a gene involved in centrosome formation." (PMID 18636107, 2008). "NEDD9-dependent FAK signaling has been previously reported in the context of cancer." (PMID 40506423, 2025). "An intriguing possibility is that endogenous levels of NEDD9 in progressing human tumors may be a determinant of response to therapeutic agents seeking to target the Warburg effect in human cancers—a point meriting further investigation." (PMID 35410460, 2022). "It is not surprising that aberrant NEDD9 expression has been linked to the prognosis of human cancers." (PMID 34432355, 2021). "We hypothesized that NOTCH activation was involved in G-MDSC-stimulated cancer stemness through NEDD9." (PMID 33710809, 2021). "Neural precursor cell expressed developmentally downregulated 9 (NEDD9) is a cytoskeletal protein molecule that is related to biological functions such as cell adhesion, migration, invasion, apoptosis, and cell cycle and promotes cancer metastasis." (PMID 33195408, 2020). "Regarding the invasion and migration of cancer cells, invadopodia formation and secretion of MMPs, the overexpression of neural precursor cell expressed developmentally downregulated 9 (NEDD9) has been suggested as a biomarker of tumor agressiveness in many types of cancer, including oral cancer." (PMID 30927923, 2019). "Upregulation of such proteins suggests mechanisms through which misregulation of NEDD9 may be involved in cancer progression." (PMID 28194179, 2017). "Moreover, NEDD9 has been proved by CHIP-Seq to be a downstream target of TGF-β signal pathway, whose activation increases NEDD9 expression and promotes cancer metastasis." (PMID 28915595, 2017). "For example, NEDD9 has been defined as critical for a response to VEGF in cancer cells." (PMID 25594051, 2014). "This is perhaps not surprising since many oncoproteins which are abundant in cancer cells are also highly expressed during embryonic development, with some being developmentally down-regulated in expression in normal adult tissue, such as NEDD9 and NEDD4." (PMID 25426952, 2014).
cancer (continued). "The focal adhesion docking protein NEDD9/HEF1/Cas-L regulates cell migration and cancer invasion." (PMID 23874939, 2013). "Given the critical role of NEDD9 in the promotion of cancer invasion, elucidation of NEDD9-specific and NEDD9-unique phosphorylation-mediated interactions is likely to be important for future assessment of NEDD9 as both a prognostic indicator and therapy target in cancer." (PMID 23874939, 2013). "Interestingly, TGFb3 is a known inducer of both periostin and NEDD9, both of which have been reported as frequently overexpressed in a variety of human cancers." (PMID 23372733, 2013). "E-cadherin is a downstream protein of NEDD9 and may be a key modulator of NEDD9-mediated cancer cell migration and invasion." (PMID 24058594, 2013). "Whether this is true for other types of cancers remains to be established; for example, reduced levels of NEDD9 transcripts characterize an MDA-MB-231 breast cancer cell line selected by serial in vivo passages for efficient metastasis to the lung in mice." (PMID 23226728, 2012). "HEF1/CAS-L/NEDD9 is a non-catalytic scaffolding protein implicated in the invasion ability of several types of cancer." (PMID 22869051, 2012). "In recent years, NEDD9 has been confirmed to contribute to the development of several cancer types." (PMID 21829474, 2011). "The GCNT2 gene has never been linked to cancer development, so we selected NEDD9 and GABBR1 as the most promising potential candidate genes." (PMID 21283797, 2011). "It will be important to determine whether Smurf2 and NEDD9 levels correlate with each other in human cancers." (PMID 20825672, 2010). "Both Smurf2 and NEDD9 are overexpressed in multiple types of cancers." (PMID 20825672, 2010). "Furthermore, NEDD9 is crucial for the formation of invasive pseudopodia required for local matrix degradation at the cancer primary site, and thus may explain the presence of magnupodia in parental MB-231 cells." (PMID 35158871, 2022). "An altered scaffolding function of NEDD9 protein, which is critical in sustaining numerous pro-oncogenic and tumor-suppressing pathways that are extensively cross-regulated, has been extensively reported in the literature in several cancer settings, including NSCLC." (PMID 35626121, 2022). "However, the mechanism behind hypoxia-promoted cancer cell migration and its regulation because of NEDD9 is still unknown." (PMID 31019460, 2019). "CPE-ΔN may have other functions as well during embryonic neurodevelopment besides neuroprotection, such as proliferation and differentiation of neuroprogenitors, since it can activate expression of other genes such as Nedd9 which is involved in cell proliferation and migration in cancer cells." (PMID 25426952, 2014). "NEDD9 can be a potent therapeutic target for cancer treatment, and ISO is a candidate to inhibit NEDD9." (PMID 40362444, 2025). "Genes differing insignificantly from healthy tissue were IMP-3, CDH1, IQGAP1, NEDD9, TKS5, WAS and ARPC4, indicating minimal alterations in their expression levels in the analyzed cancer samples." (PMID 37623256, 2023). "MALAT1 binds miR145-5p and decreases its expression, resulting in increased NEDD9 expression, as miR145-5p targets NEDD9 mRNA 3'-UTR, and cancer cell migration and invasion." (PMID 32174966, 2020). "It is noteworthy that both NEDD9 and SOX2 are recognized as HIF-1α downstream genes where they also participate in the control of cancer cell migration." (PMID 31462898, 2019). "The present studies support a role for NEDD9 as an enhancer of MMP9 secretion, invadopodia formation and cancer cell invasion." (PMID 29876004, 2018). "Notably, it was identified that neural precursor cell expressed, developmentally downregulated 9 (NEDD9, also termed HEF1 or Cas-L), a non-catalytic scaffolding protein implicated in the invasive ability of several types of cancer, is a novel target of miR-145 in PC." (PMID 25646678, 2015).
cancer (continued). "Reciprocally, these functions can better inform our understanding of the action of NEDD9, CASS4 and PTK2B in cancer." (PMID 25594051, 2014). "For historical reasons, the bulk of molecular characterizations of NEDD9, CASS4, and PTK2B have stressed their roles in cancer." (PMID 25594051, 2014). "Direct regulation of some oncogenes involved in cancer cell invasion and metastasis, like MUC1, FSCN1, NEDD9 and SOX9, by miR-145 has been identified in many cancers 90–93." (PMID 25124875, 2014). "We focused our attention on HEF1/Cas-L/NEDD9, a scaffold protein involved in invasion in several types of cancer." (PMID 22869051, 2012). "The Cas scaffolding proteins (NEDD9/HEF1/CAS-L, BCAR1/p130Cas, EFSSIN, and HEPL/CASS4) regulate cell migration, division and survival, and are often deregulated in cancer." (PMID 21765937, 2011). "NEDD9/HEF1/Cas-L is a member of the Cas protein family and was identified as a metastasis marker in multiple cancer types." (PMID 21829474, 2011). "NEDD9 associated with FAK, which is a nonreceptor tyrosine kinase that is overexpressed and activated in many cancer types." (PMID 38619434, 2024). "Several proteins involved in cytoskeleton rearrangement such as actin, TNS3, KIF23, CKAP2L, NEDD9 and PLEC were also hyperphosphorylated, indicating the known regulatory role of AXL in promoting cancer cell migration/invasion and inducing epithelial-mesenchymal transition (EMT)." (PMID 34439388, 2021). "Although NEDD9 overexpression or inhibition does not induce tumorigenesis, its expression is upregulated in many cancers." (PMID 33344223, 2020). "NEDD9 was identified to interact with MICAL1 by far western screening analysis providing a basis for further exploring the role of MICAL1 in NEDD9-induced alteration of cancer cell function." (PMID 31019460, 2019). "FOXC1 promoted metastasis of cancers by increasing expression of MMP7, NEDD9 and Snail." (PMID 29552326, 2018). "Together, the data support a negative association between important cancer targets that possess opposing functions, LKB1 on one hand, and NRP-1/NEDD9 on the other." (PMID 26701889, 2016). "In addition, we also found that the presence of HDAC7 led to the upregulation of genes related to immune processes (IL16, FCGR2A, IRAK2, CD86 and CD40, among others) and cancer (RASSF4, RAB31, NEDD9 and RASSF2, among others)." (PMID 25675295, 2015). "Intriguingly, NEDD9, CASS4, and PTK2B have been much studied as interacting partners regulating oncogenesis and metastasis, and all three are known to be active in the brain during development and in cancer." (PMID 25594051, 2014). "The described collection of functional relationships for NEDD9, CASS4 and PTK2B in AD is a generalizable approach of thinking about genotypes, phenotypes and ultimately functionality to understand diseases ranging from Alzheimer's to cancer." (PMID 25594051, 2014). "Finally, while the main focus of this review has been on the roles of NEDD9, CASS4, and PTK2B in LOAD, many of the LOAD-relevant processes can further highlight the significance of these proteins in cancer." (PMID 25594051, 2014). "In cancer, discussion of action of the NEDD9-CASS4-PTK2B scaffolding and signaling axis almost invariably focuses on the regulation of cell migration and invasion, following the upregulation of NEDD9 and activation of PTK2B in many tumors." (PMID 25594051, 2014). "Dock3 in conjunction with NEDD9 promotes EMT, mesenchymal migration and metastasis of cancer cells." (PMID 23441967, 2013). "Quantitative real-time polymerase chain reaction (qPCR) using 11 pairs of NPC biopsy samples confirmed the significant decline in GABBR1 and NEDD9 mRNA expression in the cancer tissues compared to the adjacent non-tumor tissue (p<0.05)." (PMID 21283797, 2011).
cancer (continued). "Because of the involvement of NEDD9 in key cellular functions, it is not surprising that a link has been established between its aberrant expression or activation and the aggressiveness or metastatic capacity of cancer cells." (PMID 29100287, 2017). "The interaction of NEDD9 with FAK and Src leads to the tyrosine phosphorylation of NEDD9 to generate binding sites for effector proteins, including the Rac and the Cas-Crk complex, which then regulate and activate transcription pathways involved in metastasis and cancer progression." (PMID 25646678, 2015). "Only for the protein NEDD9 there was no cancer related article found." (PMID 20224638, 2009). "Interestingly, over the past two decades, several studies have identified roles for NEDD9, CASS4, and PTK2B in these processes, but this literature is typically underappreciated in the context of neurodegenerative diseases, in contrast to the focus on this signaling cluster in cancer and metastasis." (PMID 25594051, 2014).
tumor (68 papers, 2010 to 2025). "Upregulation of MCC is associated malignant cell transformation for example in B-cells, and NEDD9 is associated to oncogenic signaling and tumor aggressiveness." (PMID 35565298, 2022). "Consistent with their findings, the high-throughput gene expression profiling of HNSCC tumor samples has shown that overexpression of NEDD9 is associated with invasive HNSCC." (PMID 30927923, 2019). "NEDD9 has been found to be diagnostic, prognostic, and predictive in different kinds of tumor types." (PMID 30544746, 2018). "Further analysis of the data revealed that NEDD9 expression was associated with several adverse prognostic markers, including estrogen receptor (ER) negativity and high tumor grade." (PMID 21829474, 2011). "NEDD9 has been linked to the EMT across various tumor types." (PMID 40362444, 2025). "If the stimulating effect of HDAC inhibitors on NEDD9 is vital to promote tumor cells’ invasion ability, we would expect that loss of NEDD9 could reverse HDAC inhibitors-induced phenotypes." (PMID 36604412, 2023). "Also, we demonstrated that LKB1-depletion was associated with elevated NEDD9 expression in our previously published lung tumor xenograft model in association with increased angiogenesis and tumor growth." (PMID 26701889, 2016). "As a transcription factor, FOXC1 promotes tumor invasion or metastasis by increasing the expression of neural precursor cell expressed developmentally down-regulated 9 (NEDD9) or matrix metalloprotease 7 (MMP7)." (PMID 40416363, 2025). "A series of previous studies have found that NEDD9 can affect epithelial mesenchymal transformation and promote tumor metastasis." (PMID 39060928, 2024). "ROBO1, KLK6, LIMK2, KLK7, NLGN4X, MBP, and NEDD9 expression levels were significantly higher in normal tissues than in tumors, demonstrating the possibility of being a tumor suppressor gene." (PMID 38137332, 2023). "As shown by whole-body gene knock-out, endogenous NEDD9 is required for tumor growth in MMTV-neu transgenic mice." (PMID 36831460, 2023). "The differential gene expression levels showed that NEDD9 expression levels were significantly higher in normal tissues than in tumors, corroborating that NEDD9 gene expression is activated before tumor formation." (PMID 38137332, 2023). "In an in vivo model, overexpression of miR-107 decreased the expression of NEDD9 and inhibited tumour growth, invasion and metastasis; however, these effects were reversed by inhibiting miR-107." (PMID 35549691, 2022). "Genetic ablation of NEDD9 results in significant signaling changes during tumor initiation and progression." (PMID 35626121, 2022). "Immunohistochemical staining revealed that NEDD9 was inhibited in tumours overexpressing miR-107, while the opposite effect was observed in tumours with miR-107 silencing (P < 0.05)." (PMID 35549691, 2022). "Although NEDD9 has been much studied in the context of tumor initiation and progression, ciliary signaling, integrin signaling, and migration, little is known about the role of this protein in DNA damage response." (PMID 35626121, 2022). "Earlier studies investigating effects of elevated NEDD9 expression on tumors’ invasiveness and metastasis subsequently concentrated research efforts on elucidating the role of upregulated NEDD9 in tumor progression." (PMID 35626121, 2022). "NEDD9 knockdown severely impaired tumor sphere formation, an in vitro indicator of self-renewal and proliferation capacities." (PMID 33710809, 2021). "We selected NEDD9 as a potential target for further experiments because our previous study found that NEDD9 was overexpressed in PAC tumor tissues." (PMID 34314382, 2021). "A NOTCH inhibitor (RO4929097) partially reduced NEDD9 expression, tumor sphere formation, and stemness-related transcription factors induced by G-MDSCs." (PMID 33710809, 2021).